SFRP4 (secreted frizzled related protein 4)
Diseases named in the same sentence as SFRP4 in open-access papers (continued):
Sharing a sentence is not in itself a finding about the gene and the disease.
tumor (continued). "Other significant DE genes with high FC(log2), unique to the study were INHBA, COL1A1, COL11A1, COMP, SFRP4 and SPP1, which were clustered in STRING network analysis and correlated with tumour-infiltrating immune cells in TIMER, suggesting a specific interaction pathway." (PMID 34824625, 2021). "SFRP4 controls WNT signaling and is thought to play a role for tumor aggressiveness." (PMID 35096608, 2021). "Second, the tumor biological relevant role of SFRP4 may be abrogated after ERG activation, for example, if ERG target genes become expressed that interfere with SFRP4 function." (PMID 32677026, 2020). "Our analysis of molecularly defined tumor subgroups revealed that the prognostic impact of SFRP4 expression was almost entirely driven by the ERG negative cancer subgroup." (PMID 32677026, 2020). "Conversely, Wnt2 and Wnt8b are downregulated at the tumor/bone interface while Wnt antagonists WIF1 and SFRP4 are overexpressed and could be responsible, at least in part, of suppression of osteoblast proliferation and enhanced bone destruction by osteoclasts." (PMID 31370265, 2019). "Our manuscript mainly discussed the average methylation rate of SFRPs (SFRP1, SFRP2, SFRP4, and SFRP5) promoters are significantly high in tumor tissue samples and the average CpG island methylation rate among different pathological levels of cutaneous SCC between these genes are different." (PMID 26394929, 2015). "In addition, encapsulated stem cells were able to trigger the expression of Wnt antagonists, such as Secreted Frizzled-related protein 4 (sFRP4), Dickkopf-1 (DKK1), and glycogen synthase kinase 3 beta (GSK-3β), downregulating the β-catenin pathway, which is involved in tumor promotion." (PMID 39936941, 2025). "However, in a study of hemangiopericytomas and various control cell lines, fibroblast growth factor 7 (FGF7) and sFRP-4 were widely expressed in all studied cell lines and tissues and were not tumour-specific." (PMID 38731904, 2024). "Since SFRP4 has a higher expression in the tumor stroma, high-grade cancer samples where cancer cells have displaced the stroma tissue might not consistently have high SFRP4 gene expression in average bulk analysis." (PMID 39511287, 2024). "However, SFRP4 expression lacked unequivocal prognostic impact in tumor subsets defined by a quantitative Gleason grade." (PMID 32677026, 2020). "The expression among tumor stages varied significantly for SFRP2, SFRP3, and SFRP4, whereas the mRNA expressions of SFRP1 and SFRP5 were not markedly different." (PMID 34205081, 2021).
cancer (76 papers, 2008 to 2026). A tumor composed of atypical neoplastic, often pleomorphic cells that invade other tissues. "Our findings show that SFRP4 gene expression is predominantly located in the stroma of high-grade cancer samples and is tightly linked to ECM remodeling." (PMID 39511287, 2024). "COX-2, WBP2, IFITM3, and SFRP4 are associated with cell proliferation and inflammation in a variety of cancers." (PMID 38239300, 2024). "A systematic review demonstrated hypermethylation of SFRP4 was a risk factor of cancer with an odds ratio (OR) of 11.41." (PMID 33878734, 2021). "Further ATRA treatment increases apoptosis of cancer cells associated with a decrease in nuclear β-catenin and increase in stromal SFRP4 in KPC mice." (PMID 34503201, 2021). "This suggests that the Wnt pathway is involved in the initiation of the cellular transition, because SFRP4 is a Wnt pathway regulator whose expression has been found associated with various cancer types." (PMID 34283835, 2021). "Strong SFRP4 staining was significantly linked to increased cell proliferation as measured by Ki67 labeling index in all cancers (p < 0.0001)." (PMID 32677026, 2020). "In ERG-positive cancers, an unequivocal association was only found between SFRP4 up regulation and positive surgical margin (p = 0.0104) but not with any other histological parameter nor with patient prognosis." (PMID 32677026, 2020). "The high negative correlation between SFRP4 expression and spermine and citrate in our study cohort further supports SFRP4 expression to be associated with aggressive cancer." (PMID 29079735, 2017). "We showed increased expression of SFRP4 in high Grade Group compared with low Grade Group cancer samples, as well as an association between SFRP4 expression and risk of biochemical recurrence and metastasis after radical prostatectomy." (PMID 29079735, 2017). "Patients with cancers who had lost membrane SFRP4 expression were associated with an earlier death from their disease (p = 0.016)." (PMID 22363760, 2012). "Similar to our data, a trend has been observed by other studies where down regulation of sFRP4 expression was similarly associated with stage and grade of the cancer." (PMID 23039795, 2012). "To assess our hypothesis, we silenced SFRP4 in cancer-associated fibroblasts (CAFs) using three siRNAs and examined the effects on BC cells." (PMID 38686196, 2024). "SFRP4 has been documented to be associated with the Wnt pathway in a variety of cancers." (PMID 38239300, 2024). "We also confirmed that higher SFRP4 gene expression is associated with cancer aggressiveness." (PMID 39511287, 2024). "Several mutations of SFRP4 gene are reported as part of Pyle disease etiology and altogether 105 mutations can be found in different cancers, interestingly the ones that have been characterized as pathogenic all result in frameshift or nonsense indicating that the protein is lost." (PMID 38993819, 2024). "A hypothesis to explain the association between SFRP4 gene expression and high Grade Groups, as well as recurrence and metastasis after prostatectomy, could therefore be that SFRP4 increases the cancer cell’s ability to metastasise to bone." (PMID 29079735, 2017). "The paradoxical growth retardation seen in previous studies of cancer cell lines might be outweighed by an increased ability to metastasize to bone, which can explain why high SFRP4 expression is associated with recurrence after prostatectomy." (PMID 26522007, 2015). "The aim of this study is to evaluate the relationship between the methylation and expression of APC, SFRP1, SFRP2, SFRP4, and SFRP5 genes involved in the Wnt signaling pathway and the risk of cancer development in IBD." (PMID 40521787, 2025). "A previous study has shown that restoration of SFRP4 secretion by pancreatic stellate cells reduced Wnt–β-catenin signalling in cancer cells and their invasive ability." (PMID 40640495, 2025).
cancer (continued). "While SFRP4+ CAF subsets have been reported in several cancer types, F4 showed limited similarity to published iCAF/myCAF signatures." (PMID 41378308, 2025). "Although SFRP4 is conventionally viewed as a Wnt antagonist, both our data and previous studies indicate a context-dependent agonistic role in cancer." (PMID 40565036, 2025). "The sFRP4 has garnered significant interest as a therapeutic target for metabolic diseases and cancer due to its mechanism of action." (PMID 40920763, 2025). "The possible functions of the main signalling pathways involving sFRP4 in cancer development were further highlighted by the pathway enrichment analysis." (PMID 40920763, 2025). "Although SFRP4 is traditionally classified as a Wnt antagonist, emerging evidence underscores its context-dependent and even paradoxical roles in cancer." (PMID 40565036, 2025). "Our study identified potential compounds for high-potential drug candidates against sFRP4, demonstrating their effectiveness in cancer cell death and upregulating sFRP4 expression through improved drug design methods and experimental studies." (PMID 40920763, 2025). "Collectively, our data demonstrate that PKA-mediated phosphorylation of SFRP4 enhances cancer stemness-related properties in GC through Wnt signaling." (PMID 40565036, 2025). "We found that methylation of the SFRP4 gene promotor was both significantly negatively correlated with gene expression and reduced in cancer compared to normal samples." (PMID 39511287, 2024). "This was in contrast to the corresponding tissue data from Prensner which showed decent expression levels of SFRP4 for normal, cancer and metastatic prostate tissue." (PMID 39511287, 2024). "SFRP4 mRNA was predominantly located in cancer stroma, produced by fibroblasts and smooth muscle cells, and co-expressed with extracellular matrix components." (PMID 39511287, 2024). "SFRP4 was also increased in cancer stroma from relapse patients compared to relapse-free patients (log2FC = 1.97, p = 1.33 × 10−119)." (PMID 39511287, 2024). "The best protein biomarker combination of epithelial AGR2, AGR3, CEAM5, stromal CD90, and SFRP4 produced an AUC value of 0.95 in distinguishing cancer from non-cancer." (PMID 38595814, 2024). "Multiple different carcinoma cell lines that were transfected with recombinant SFRP4 demonstrated increased sensitivity to chemotherapeutics, decreased aggressiveness and invasiveness." (PMID 38993819, 2024). "It has been reported that SFRP2 and SFRP4 levels are tightly correlated with each other, which shares a common gene program across multiple cancers." (PMID 35372028, 2022). "The mean SFRP4 expression of submucosal cancer tissue in the extragastric recurrence group (−2.8 ± 1.3) was significantly higher than that in the control group (−4.3 ± 1.6) (p = 0.047)." (PMID 35683460, 2022). "In both the extragastric recurrence group (−2.8 ± 1.3 vs. −6.6 ± 1.8, p < 0.001) and the control group (−4.3 ± 1.6 vs. −7.1 ± 1.5, p < 0.001), SFRP4 expression was significantly higher in the submucosal cancer tissue than that in the mucosal layer." (PMID 35683460, 2022). "Serum SFRP4 levels were significantly lower in cancer groups compared to the control group (2.1 ± 0.3 and 2.2 ± 0.4 in OC and EC (respectively) vs 2.9 ± 0.5 in the control group, p = 0.05)." (PMID 35461390, 2022). "In these 137 patients, high expression of SFRP4 was found in 96 (70.07%) cancer tissues and 76 (55.47%) paracancerous tissues, and SFRP4 expression was considerably elevated in cancer tissues compared to paracancerous tissues (P=0.012)." (PMID 35847366, 2022). "Secretory frizzled-related protein 4 (SFRP4), a member of the secretory frizzled-related protein family, is a Wnt signaling inhibitor that plays a key role in cancer." (PMID 35847366, 2022). "SFRPs are known as cancer suppressors by block Wnt signaling pathway, whose promoter methylation can reduce the normal expression of SFRP4 and promote HCC." (PMID 33878734, 2021).
cancer (continued). "Here, we used multiple clinical genomic cohorts of GC to validate the finding that SFRP4 is over-expressed in more invasive cancers." (PMID 33277667, 2021). "There was a clear increase in circulating SFRP4 levels in patients who develop cancer recurrence that occurs very early after curative resection and was maintained, in some cases for years, before the clinical diagnosis of recurrence." (PMID 33277667, 2021). "Cluster 0 cells showed fibroblast signatures (RGS5 and NDUFA4L2), cluster 2 cells had strong expression of cancer associated fibroblast (CAF) markers (LUM, SFRP4, and COL1A1), and cluster 5 cells expressed myofibroblast markers (MYH11, TAGLN, and ACTA2)." (PMID 33662621, 2021). "Epigenetic downregulation of secreted frizzled-related proteins and SFRP4 by promoter methylation has been described in some cancer types however in GC this seems to be restricted to the SFRP2 gene." (PMID 33277667, 2021). "SFRP4 staining was seen in 64.9% of tumors and classified as weak in 33.2%, moderate in 23.9% and strong in 7.8% of cancers." (PMID 32677026, 2020). "Compensatory SFRP4 upregulation in case of a highly activated Wnt pathway represents a likely explanation for high SFRP4 levels in aggressive cancers." (PMID 32677026, 2020). "That SFRP4 expression still largely lacks prognostic impact in cancers with identical traditional quantitative Gleason grade demonstrates the statistical power of a thorough morphological assessment." (PMID 32677026, 2020). "Only 7.7% and 1.8% of AR-negative, but 33.1% and 13.1% of strongly AR expressing cancers showed a moderate or strong SFRP4 immunostaining (p < 0.0001)." (PMID 32677026, 2020). "Subset analysis of cancers with identical Gleason score revealed a prognostic role of SFRP4 in subsets of cancers with Gleason grade 4 + 3 (p = 0.0005)." (PMID 32677026, 2020). "To further analyze if sFRP4 is truly involved in regulating stemness and pluripotentiality, we chose to study the effect of sFRP4 suppression in a non-cancer context." (PMID 30591679, 2018). "In our study cohort, there was significantly higher SFRP4 expression in cancer samples compared with normal samples (t-test p < 0.001)." (PMID 29079735, 2017). "This study investigated molecular signals essential to sustain cancer stem cells (CSCs) and assessed their activity in the presence of secreted frizzled-related protein 4 (sFRP4) alone or in combination with chemotherapeutic drugs." (PMID 28536422, 2017). "The aberrant expression of miR-135b-5p and secreted frizzled-related protein 4 (SFRP4) has been revealed to be involved in various cancers." (PMID 28977937, 2017). "Western blot analysis of sFRP4 protein levels determined that the normal cell line IOSE expressed significantly higher levels of sFRP4 (p < 0.001) compared to the cancer cells." (PMID 23039795, 2012). "Our transfection and silencing experiments confirmed that sFRP4 appeared to have a direct influence on the chemo-response of cancer cells." (PMID 23039795, 2012). "As a result, we found that 3′-phosphoadenosine 5′-phosphosulfate synthase 2 (PAPSS2), γ-tubulin gene 2 (TUBG2), NTRK2, B4GALT1, and OSMR as well as SFRP4 harbored cancer-specific methylation with high frequencies (>30%)." (PMID 19662090, 2009). "Since from the outset of work with SFRP-4, its role seemed to be in the induction of apoptosis in various systems, its future potential in cancer therapy justifies active research on its function in different developmental contexts." (PMID 18452624, 2008). "In most cancers, it was found that SFRP4 expression is either reduced or suppressed." (PMID 40521787, 2025). "SFRP4 has been extensively studied in the context of the Wnt-pathway and cancer development." (PMID 39511287, 2024). "SFRP4 has been found to prevent malignant tumor proliferation and metastasis." (PMID 35847366, 2022).
cancer (continued). "Finally, the finding of altered expression in serum level of SFRP4 evaluated in our study, resulting in a lower serum SFRP4 expression in cancer groups compared to the control one, seems to agree with recent literature data." (PMID 35461390, 2022). "However, a recent study showed that some subtypes of SFRPs, such as SFRP2 and SFRP4, tended to be overexpressed in cancer." (PMID 35683460, 2022). "By IGV analysis, it was found that SFRP4 carries four SNPs in the cancer sample datasets." (PMID 33891491, 2021). "Knockdown of SFRP4 in PSCs increases the nuclear β-catenin, suggesting that stromal SFRP4 may induce cancer cell death and may inhibit Wnt-β-catenin signaling." (PMID 34503201, 2021). "It is possible, that SFRP4 is upregulated in such cancers in an attempt to regain growth control." (PMID 32677026, 2020). "SFRP4 is typically described as a tumor suppressor gene with a role in many cancer types." (PMID 32677026, 2020). "First, compensatory SFRP4 upregulation might also appear in aggressive cancers with activated Wnt signaling due to reasons other than ERG fusion." (PMID 32677026, 2020). "SFRP4 has also been shown to inhibit proliferation and metastatic potential in malignant neoplasms." (PMID 28977937, 2017). "Aberrant Wnt signaling has been implicated in tumorigenesis, and inhibition of components of this pathway such as SFRPs, and more specifically, SFRP4, may be a potential target for cancer therapy." (PMID 28977937, 2017). "The existing literature indicated that SFRP4 might increase the chemotherapeutic response and may be a potential drug that is used to destroy cancer cells." (PMID 28977937, 2017). "Promoter hypermethylation and downregulation of SFRP4 has been illustrated in various cancers." (PMID 28977937, 2017). "Consistently, sFRP4 has been found to be downregulated in several human cancers." (PMID 25844602, 2015). "SFRP4 expression was lost in all cancer cell lines compared to HOSE6-3." (PMID 22363760, 2012). "We can therefore not conclude on whether our observed associations between SFRP4 levels and stroma in cancer samples are generalizable across all ethnicities." (PMID 39511287, 2024). "Third, given that at least some other SFRP family members can have both suppressive or activating roles on Wnt signaling activity depending on their individual expression levels, it cannot be excluded that upregulated SFRP4 might have a Wnt activator role specifically in ERG-negative cancers." (PMID 32677026, 2020). "Whilst SFRP4 plasma expression was not predictive of outcome, its loss of expression from healthy to cancer still supports the findings achieved by RT-qPCR, Western-blot and IHC, and is probably mainly due to lower sample size and shorter follow-up data than our large IHC cohort." (PMID 22363760, 2012). "We investigated the function of two markers of the fibroblastic transition highly induced by cancer cells: a long non-coding RNA LINC01614 and a Wnt signaling modulator SFRP4." (PMID 41595155, 2026). "Other marker genes of SFRP4+ CAFs, such as OGN and CLU, also influenced cell proliferation and invasion and cancer initiation, respectively." (PMID 38686196, 2024). "For example, Oncotype DX tests the expression of 5 reference genes and 12 cancer-related genes, including BGN (biglycan), COL1A1, FLNC, and SFRP4 (secreted frizzled related protein 4)." (PMID 38255186, 2023). "SFRP4 and OGN have been identified as the core genes of EC and cancer cell-derived exosome progression, which are closely related to the occurrence and progression of EC." (PMID 37352032, 2023). "It would hence be of interest to look at the protein expression data in cancers for CTHRC1 and the now identified genes of interest, POSTN, MMP13, SFRP4, ADAMTS16 and FNDC1." (PMID 36190948, 2022). "Of the EMT pathway, the genes IL-6, SFRP4, FZD8, ADAM12, and CCN2 are known to promote cancer cell invasion and migration in multiple types of cancers." (PMID 35505422, 2022).